CHD7 (chromodomain helicase DNA binding protein 7)
Diseases named in the same sentence as CHD7 in open-access papers (continued):
Sharing a sentence is not in itself a finding about the gene and the disease.
autism (13 papers, 2017 to 2024). Persistent deficits in social interaction and communication and interaction as well as a markedly restricted repertoire of activity and interest as well as repetitive patterns of behavior. "Our study provides crucial evidence to support the notion that the intronic variant site of CHD7 is a potential autism susceptibility site, shedding new light on identifying the functions of intronic variants in genetic studies of autism." (PMID 33948885, 2021). "Our study provides crucial evidence supporting the notion that the intronic variant of CHD7 is potentially an autism susceptibility site, shedding new light on identifying the functions of intronic variants in genetic studies of autism." (PMID 33948885, 2021). "The proper neural differentiation and development of human NPCs and neurons were severely affected by the intronic variant, providing crucial evidence supporting the notion that the intronic variant site of CHD7 is a potential autism susceptibility site." (PMID 33948885, 2021). "Variants in CHD7 have been described in subjects with both autism and ID, and many CHARGE patients show hypoplasia of the cerebellum." (PMID 32341405, 2020). "Thus, the intronic variant identified in autism patients indeed plays a critical role in regulating the function of CHD7 by down-regulating the mRNA level and disrupted alternative splicing patterns." (PMID 33948885, 2021). "Examples of these genes include CHD7, ANKRD11, and SON which are robustly associated with both autism and severe developmental disorders." (PMID 36702863, 2023). "Our study provides supporting evidence showing Chd7-dependent regulation of transcription is involved in the pathogenesis of autism." (PMID 28317875, 2017). "Regulatory inference using the Genie3 algorithm identified direct regulation of IGF1 by SIK1, MFRP, CHD7, NIPBL, EXOC5, and ARID2, with SIK1 and SPARCL1 significantly downregulated in autism brain organoids, potentially affecting IGF1 expression." (PMID 39376742, 2024). "In addition, the mRNA levels of brain development‐related genes CHD7 and oligodendrocyte development‐related genes Olig2 and MBP were significantly decreased in the VPA‐induced autism model group (p < 0.01), and improved after AVP treatment (p < 0.01)." (PMID 36239083, 2022). "The prevalence of the pathogenic CHD7 variant (85%) and the ratio of truncating versus non-truncating CHD7 mutations (30%/70%) were similar in the 13 individuals with CS and autism (ADI-R), the 13 patients without autism, and the entire group of 46 patients (data not shown)." (PMID 32493418, 2020).
autism spectrum disorder (11 papers, 2012 to 2025). A spectrum of developmental disorders that includes autism, and Asperger syndrome. "Recent research has identified CHD7 variants in individuals with isolated features such as autism spectrum disorder or gonadotropin-releasing hormone deficiency." (PMID 38790272, 2024). "CHD7 variants have already been reported in individuals with isolated phenotypical features, including autism spectrum disorder or gonadotropin-releasing hormone deficiency." (PMID 38790272, 2024). "Approximately 30% of CHARGE-associated Chd7 mutations lie within functional domains including the ATPase domain and the percentage of Chd8 point mutations within the ATPase domain associated with autism spectrum disorders is 8%." (PMID 38512854, 2024). "For instance, Tbr1, Chd7, and Hdac2 are autism spectrum disorder risk genes." (PMID 36791184, 2023). "CHD proteins play an important role in neurodevelopment, as pathogenic variants in CHD1, CHD2, CHD4, CHD7 and CHD8 have been associated with a range of neurological phenotypes, including autism spectrum disorder (ASD), intellectual disability (ID) and epilepsy." (PMID 29962935, 2018). "We previously demonstrated that a part of human CHD7 interacts with a part of human CHD8, another chromodomain helicase DNA binding protein presumably being involved in the pathogenesis of neurodevelopmental (NDD) and autism spectrum disorders (ASD)." (PMID 23285124, 2012).
colorectal cancer (11 papers, 2014 to 2023). A primary or metastatic malignant neoplasm that affects the colon or rectum. "Equally notable are CHD7 mutations, previously identified within neuroblastoma and colorectal cancer narratives." (PMID 37314494, 2023). "A series of cellular experiments and mouse tumor‐bearing experiments were conducted to reveal the regulatory function of CHD7 on the growth of colorectal cancer cells." (PMID 35789070, 2022). "We experimentally demonstrated that CHD7 promotes the growth of colorectal cancer cells in vitro and in vivo." (PMID 35789070, 2022). "Thus, functional analysis and identification of target genes and upstream regulators of CHD7 in CHD7-high expression tumors including liver and colorectal cancer may be of interest in this context." (PMID 27955690, 2016). "For example, circREEP3 upregulation recruited the chromatin remodeling protein CHD7 to activate FKBP10 transcription and drive colorectal cancer progression, and the FKBP10 protein was recognized as a glioma antigen for anti-glioma mRNA vaccine production." (PMID 36463181, 2022). "Chromatin remodeler CHD7, a somatic driver candidate in colorectal cancer (CRC), promotes CRC cell growth by binding target gene promoters, encouraging an open chromatin conformation and subsequent transcription, whereas CHD7 knockdown inhibits CRC cell growth." (PMID 37444571, 2023).
glioma (11 papers, 2016 to 2025). A benign or malignant brain and spinal cord tumor that arises from glial cells (astrocytes, oligodendrocytes, ependymal cells). "In the same article, low CHD7 was associated with increasing glioma grade and poor patient prognosis." (PMID 33869187, 2021). "CHD7 is highly expressed in gliomas, and CHD7 overexpression increased proliferation and maintained the stemness of neural stem cells (NSCs) and neural precursor cells (NPCs)." (PMID 40599851, 2025). "CHD7 is also upregulated in gliomas, and mechanistic studies demonstrated that CHD7 overexpression enhanced cell migration and invasion in vitro and tumor growth in vivo." (PMID 31769422, 2019). "Consistent with the TCGA interrogation, we confirmed increased CHD7 mRNA levels in glioma tissues by qRT-PCR." (PMID 30850678, 2019). "Here, we show that CHD7 is up-regulated in human glioma tissues and we demonstrate that CHD7 knockout (KO) in LN-229 glioblastoma cells suppresses anchorage-independent growth and spheroid invasion in vitro." (PMID 30850678, 2019). "Taken together, these results suggest that CHD7 is up-regulated in gliomas and its expression is highly heterogeneous in cultured glioblastoma cell lines." (PMID 30850678, 2019). "Collectively, our data demonstrate that CHD7 is an important factor in the proliferation and stemness maintenance of NSPCs, and CHD7 is a promising therapeutic target for the treatment of gliomas." (PMID 27955690, 2016). "To test the function of CHD7 in human glioma, we firstly examined the CHD7 gene expression in normal astrocytes, NSPCs (human fetal brain derived), glioma cells (U87MG, U251), and GICs." (PMID 27955690, 2016). "This study also revealed that silencing CHD7 diminished the proliferation of glioma initiating cells, suggesting that CHD7 could be a potential therapeutic target of gliomas." (PMID 40599851, 2025). "Conversely, functional CHD7 is suspected to trigger tumorigenesis in gliomas." (PMID 40599851, 2025). "Another study found that CHD7 is highly expressed in human gliomas." (PMID 28649742, 2017). "Furthermore, in silico database analysis showed that, among members of the CHD family, CHD7 is highly expressed in human gliomas." (PMID 27955690, 2016). "Interestingly, high levels of CHD7 gene expression in human glioma initiating cells (GICs) compared to normal astrocytes were revealed and gene silencing of CHD7 decreased GIC proliferation." (PMID 27955690, 2016). "Meanwhile, miR-22 transferred from TAMs to glioma stem cells was able to promote mesenchymal phenotypes and induce radiotherapy resistance by targeting the chromodomain helicase DNA-binding protein 7 (CHD7), a chromodomain enzyme that maintains the proneural phenotype in glioblastoma." (PMID 35805995, 2022). "Finally, a recent report demonstrated that hypoxic microenvironments within the GBM tumor mass may repress CHD7 expression in glioma-initiating cells and, as a response, induce angiogenesis." (PMID 33869187, 2021). "To investigate whether CHD7 is relevant for tumor development and progression, we analyzed whether perturbation of CHD7 protein levels affects the tumorigenic potential of glioblastoma cells in an orthotopic xenograft murine glioma model." (PMID 30850678, 2019). "Finally, functional analyses of CHD7 especially in human gliomas and GICs, may help pave the way for evaluating CHD7 as a therapeutic target." (PMID 27955690, 2016). "Correlation analysis revealed that TSPAN4 was positively correlated with ITGB1, GDF15, ITGA3 and ITGA6, and negatively correlated with CHD7, ASPDH, TMEM8B and GHITM in glioma." (PMID 39723210, 2024). "Altogether, these results show that CHD7 is up-regulated in at least a subset of gliomas irrespective of the grade." (PMID 30850678, 2019).
glioma (continued). "In addition, in TCGA database analysis, the overall survival of high-CHD7 expression patients tended to be shorter compared to that of low-CHD7 expression patients in GBM (data not shown), suggesting that CHD7 may support the proliferation of glioma cells and GICs." (PMID 27955690, 2016).
deafness (10 papers, 2010 to 2024). An inherited or acquired condition characterized by the complete loss of the ability to hear from one or both ears. "Molecular analysis, using a whole exome sequencing panel [WESHL panel v2.0] containing 146 deafness genes, identified a heterozygous CHD7 variant [NM_017780.4]: c.8077-2A>T." (PMID 38790272, 2024). "The proband in family 694 (CHD7 c.5050G > A variant) had congenital profound deafness associated with inner ear anomalies." (PMID 27562378, 2016). "The original phenotypic screen investigating Chd7+/Whi mutants identified deafness due to semicircular canal defects which were fully penetrant, and occasional heart defects, choanal atresia, cleft palate and eye defects." (PMID 36232804, 2022). "The Chd7tm2a constitutive model, and corresponding conditional line Chd7tm2d(EUCOMM)Wtsi which can be derived from it, has been extensively used to investigate CHD7-dependent cardiogenesis, neuronal function and deafness." (PMID 36232804, 2022). "In summary, we demonstrate the critical role of CHD7 in regulating human otic lineage differentiation and deafness gene expression." (PMID 36396635, 2022). "Therefore, we believe that the deafness genes identified in this vestibular organoid system could serve as good candidate genes for future studies in cochlear CHD7 disease models." (PMID 36396635, 2022).
DiGeorge syndrome (10 papers, 2011 to 2023). "Genetic testing and chromosomal microarray can help to identify conditions such as 22q11.2 deletion syndrome (22q11.2 hemizygosity), CHARGE (CHD7 mutations), or FOXN1 deficiency (FOXN1 mutations)." (PMID 33987750, 2021). "Evidence for the role of CHD7 and TBX1, the causative gene of 22q11.2 deletion syndrome, has been shown in the embryonic development of the thymus in animal models." (PMID 26544072, 2015). "In addition, 5 of 20 patients who were clinically suspected of 22q11.2 deletion syndrome but with neither a 22q11.2 deletion nor a TBX1 gene mutation had a CHD7 mutation." (PMID 27957375, 2016). "These syndromes mainly include Townes–Brocks (SALL1), CHARGE (CHD7), Fraser (FRAS1), and DiGeorge syndromes (del22q11)." (PMID 28003020, 2016).
small cell lung carcinoma (9 papers, 2010 to 2022). Small cell lung cancer (SCLC) is a highly aggressive malignant neoplasm, accounting for 10-15% of lung cancer cases, characterized byrapid growth, and early metastasis. "On one hand, mutations that activate CHD7 have been found in small cell lung cancer in response to tobacco smoke, and high CHD7 expression is also found in cutaneous T-cell lymphoma." (PMID 33869187, 2021). "Interestingly, CHD7 duplications have been suggested to be a driver mutation identified in small-cell lung cancer, one of the most highly metastatic and aggressive types of cancer." (PMID 30850678, 2019). "Moreover, rearrangements at CHD7 locus have recently been associated to small-cell lung cancer." (PMID 20925924, 2010). "An in-frame duplication of exons 3–7 of CHD7 and PVT1-CHD7 fusion has been identified in small cell lung cancer cells." (PMID 35467222, 2022). "For instance, fusion of the 5' region of the PVT1 lncRNA gene to the CHD7 chromatin remodeler gene likely results in CHD7 gain-of-function in small cell lung cancer." (PMID 33329688, 2020). "CHD7 is found as a highly expressed fusion protein in small cell lung cancers." (PMID 31112698, 2019). "A genomic study of small cell lung cancer with complex tobacco exposure identified the tandem replication of CHD7 exons 3–8 and a cell line with PVT1-CHD7 fusion." (PMID 34381020, 2021).
cryptorchidism (8 papers, 2017 to 2024). The failure of one or both testes of a male fetus to descend from the abdomen into the scrotum during the late part of pregnancy. "In a study of 40 patients with idiopathic hypogonadotropic hypogonadism (IHH), two adult patients with cryptorchidism, abnormal testicular, and/or abnormal penis were identified to carry CHD7 variants." (PMID 39285472, 2024). "Patient 4, an 18-year-old male with CHH and the associated clinical characteristics of cryptorchidism and micropenis, was found to carry the novel AD p.Arg2400Trp variant in the CHD7 gene." (PMID 32982993, 2020). "The incidence of cryptorchidism in patients with FGFR1, ANOS1, and CHD7 mutations is 50–60%, 38.1–66%, and 50–70%, respectively." (PMID 33354214, 2020). "In our study, we identified CHD7 variants in 3 patients with the phenotype of micropenis, cryptorchidism, or gonadal dysgenesis, no further clinical phenoypes were recorded." (PMID 39285472, 2024). "Patients carry CHD7 variants may also present with microphallus, cryptorchidism, and hypospadias without other malformations." (PMID 39285472, 2024). "The greater the expression of the CHD7 gene is, the more obvious the clinical features of patients with IHH, especially the symptoms of cryptorchidism, small phallus, and hypospadias in childhood." (PMID 35090434, 2022).
breast carcinoma (7 papers, 2017 to 2025). "CHD7 was the most upregulated CHD gene in breast cancer and was significantly associated with aggressiveness and poor prognosis of patients." (PMID 28649742, 2017). "We validated that higher mRNA levels of CHD7 were also significantly associated with shorter overall survival of METABRIC breast cancer patients (P < 0.001)." (PMID 28649742, 2017). "We found that higher mRNA levels of CHD7 were significantly associated with shorter overall survival of TCGA breast cancer patients (P < 0.05)." (PMID 28649742, 2017). "We found that higher expression of CHD7 was significantly associated with shorter disease‐free survival (P < 0.001) in METABRIC breast cancer patients." (PMID 28649742, 2017). "The chromatin remodeler CHD7 is one of the most commonly amplified CHD genes in breast cancer, and mRNA expression levels of CHD7 are significantly upregulated in basal-like breast cancer." (PMID 32241272, 2020). "The same study also showed that overexpression of CHD7 was more prevalent in aggressive subtypes of breast cancer, being significantly correlated with high tumor grade and poor prognosis." (PMID 30850678, 2019). "We also found that CHD7 was overexpressed (Z‐score ≥ 1) in more than 50% of luminal B and basal‐like breast cancers." (PMID 28649742, 2017). "CHD7 was dramatically more highly expressed in advanced stages and in higher grades of breast cancer." (PMID 28649742, 2017). "To assess the contribution of endogenous CHD7 overexpression on the transformation of human breast cancer, we examined the effects of knocking down CHD7 in HCC1187 and SUM102 cells." (PMID 28649742, 2017). "Overexpression of CHD7 was more prevalent in aggressive subtypes of breast cancer and was significantly correlated with high tumor grade and poor prognosis." (PMID 28649742, 2017). "We found that CHD7 was the most commonly gained/amplified and mutated, whereas CHD3 was the most deleted across the majority of tumor types, including breast cancer." (PMID 28649742, 2017). "Also, mRNA expression levels of CHD7 were significantly higher in basal‐like breast cancers (P < 0.01)." (PMID 28649742, 2017). "Knockdown of CHD7 inhibited cell proliferation in breast cancer cell lines." (PMID 28649742, 2017). "Notably, among nine CHDs, CHD7 was overexpressed (Z‐score ≥ 1) in 71.54% of TCGA basal‐like breast cancers, compared to 20.49% of luminal A subtype (P < 0.01)." (PMID 28649742, 2017). "Development of E3 ligases for CHD7 degradation may be beneficial for breast cancer treatment." (PMID 41278204, 2025). "Thus, we next examined CHD7 expression in a panel of breast cancer cells." (PMID 28649742, 2017). "In this study, we revealed that CHD7 likely regulates a small set of oncogenes, such as NRAS and MYCN, in breast cancer." (PMID 28649742, 2017). "We next performed qRT‐PCR assays and demonstrated that mRNA expression levels of CHD7 in HCC1187 and SUM102 breast cancer cell lines were more than twofold higher than that in MCF10A cells (data not shown)." (PMID 28649742, 2017). "We also found that CHD7 and SOX2 (3q26) were likely cogained/amplified (P < 0.0001) in breast cancer." (PMID 28649742, 2017). "Knockdown of CHD7 inhibits cell proliferation and decreases gene expression of several CHD7 targets, including NRAS, in breast cancer cell lines." (PMID 28649742, 2017). "We found that CHD7 expression was positively correlated with a small subset of classical oncogenes, notably NRAS, in breast cancer." (PMID 28649742, 2017). "Non-functional studies:Amplification of CHD7 represents around 11% breast cancer patientsAmplifications are more prevalent in aggressive breast cancer subtypes, correlating with high tumor grade and poor prognosis." (PMID 41278204, 2025). "CHD7 is the most amplified CHD protein, represented in around 11% breast cancer patients and its amplifications are more prevalent in aggressive breast cancer subtypes, correlating with high tumor grade and poor prognosis." (PMID 41278204, 2025).
breast carcinoma (continued). "Compared with MCF10A, an immortalized but nontumorigenic breast epithelial cell line, mRNA levels of CHD7 were more than twofold higher in 19 breast cancer cell lines, nine of them belonging to the basal subtype." (PMID 28649742, 2017). "Furthermore, CHD7 was overexpressed (Z‐score ≥ 1) in 33.96% and CHD3 was underexpressed (Z‐score ≤ −1) in 35.1% of TCGA breast cancers." (PMID 28649742, 2017). "Furthermore, although the splicing vector pSAD was initially developed to study the breast cancer genes BRCA1 and BRCA2, it has also been demonstrated to be a powerful tool to test other disease genes such as SERPINA1, CHD7, and UGT1A1, as well as others currently under investigation." (PMID 32211025, 2020). "Furthermore, expression of the classical breast cancer oncogenes EGFR (epidermal growth factor receptor) and v‐Myc avian myelocytomatosis viral oncogene neuroblastoma‐derived homolog (MYCN) was also positively correlated with CHD7 expression, with Spearman's r = 0.24 and 0.12, respectively." (PMID 28649742, 2017).